ENSG00000294881 (novel transcript)
Gene: Long non-coding RNA gene on chromosome 14 (97,170,476 to 97,208,287, reverse strand). Ensembl gene ENSG00000294881.
Gene Ontology:
Biological process: SRP-dependent cotranslational protein targeting to membrane, signal sequence recognition
Cellular component: signal recognition particle, endoplasmic reticulum targeting